MSI2 (musashi RNA binding protein 2)
Diseases named in the same sentence as MSI2 in open-access papers (continued):
Sharing a sentence is not in itself a finding about the gene and the disease.
colon cancer (12 papers, 2020 to 2026). "Next, we used MSI2 knockout (MSI2-/-) transgenic and wild-type (MSI2+/+) mice to construct a colitis-associated colon cancer model by administering azoxymethane (AOM) intraperitoneally and feeding with 3% DSS for three cycles." (PMID 38041016, 2023). "Studies have shown that Aza-9 binds to MSI2, thereby inhibiting the proliferation of colon cancer cell lines, inducing apoptosis and autophagy, and down-regulating Notch and Wnt signaling." (PMID 40535805, 2025). "Based on these studies, we first found that MSI2 was expressed at higher levels than normal tissues in many tumors, such as lung, breast, and colon cancers, and especially in all types of NSCLC than in normal lung tissues by bioinformatics analysis." (PMID 38645664, 2024). "To determine the MSI2 mRNA targets specific in colon cancer, we investigated the transcripts regulated by MSI2 in NSCLC A549 cells as control and found 20 candidate genes in total." (PMID 35153752, 2021). "Collectively, these results demonstrated that the depletion of MSI2 delayed the G1-to-S phase transition by regulating the amount of Cyclin E1 expression in colon cancer HCT116 cells, thus suppressing its proliferation." (PMID 35153752, 2021). "As a control, no selectivity was found in WT and MSI2 knockout A549 cells treated with either compounds, further supporting the functional targeting of MSI2 in colon cancer cells by these compounds." (PMID 35153752, 2021). "To better understand the role of MSI2 in human colon cancer, we profiled the global gene expression of MSI2 knockout HCT116 cells using RNA sequencing." (PMID 35153752, 2021). "We examined the differentially expressed proteins by proteomic analysis and the CAC model of colon cancer in transgenic mice with intestinal epithelial overexpression of MSI2 was established, MSI2 was found to increase the expression of HMGB1 in vitro and in vivo." (PMID 38347600, 2024). "In addition, MSI2 is overexpressed in a variety of solid tumors and promotes tumor progression, such as that in colon cancer, lung cancer, pancreatic cancer, and liver cancer." (PMID 36713428, 2022). "To identify MSI2-binding RNA targets in colon cancer cells, we took advantage of the MSI2 knockout cells and investigated the global changes of mRNA and protein by a combination of mass spectrometry and RNA sequencing, and the knockout and WT A549 cells were included as a control in parallel." (PMID 35153752, 2021). "Immunohistochemical results showed that compared with normal colon tissues, MSI2, EZH2, and NCL were significantly higher expressed in colon cancer tissues except TERT." (PMID 40535805, 2025). "Recent studies on colon cancer cell lines have suggested that both USP10 and MSI2 proteins are upregulated." (PMID 32828126, 2020). "In addition, the protein levels of MSI2 and HMGB1 were increased in primary CRC specimens compared with normal adjacent tissues in our clinical CRC specimens and CPTAC Colon cancer dataset." (PMID 38347600, 2024). "However, the depletion of MSI2 did not attenuate the cytotoxicity of both (−)gossypol and Ro 08-2750, indicating that there are other functional targets of the compounds in colon cancer cells." (PMID 35153752, 2021).
gastric cancer (11 papers, 2020 to 2025). A primary or metastatic malignant neoplasm involving the stomach. "Other tumor types in which MSI2 overexpression has been linked to increased aggressiveness include hepatocellular carcinoma and gastric cancer." (PMID 34237057, 2021). "Moreover, LINC00942 has been implicated in promoting chemoresistance in gastric cancer by impeding the degradation of oncoprotein MSI2." (PMID 38589454, 2024). "Elevated LncRNA LINC00942 conferred gastric cancer (GC) chemoresistance by activating the MSI2/c-Myc axis to induce stemness and suppress apoptosis of GC cells." (PMID 38688909, 2024). "According to a previous study based on microarray and RT-PCR, MSI2 expression increased slightly relative to normal tissue, but it is still used as a biomarker for gastric cancer." (PMID 32848739, 2020). "It boosts MSI2 levels by blocking its degradation through ubiquitin, which in turn stabilizes c-Myc mRNA in an m6A-dependent way, helps prevent apoptosis, promotes stem cell traits, and boosts resistance to cisplatin in gastric cancer." (PMID 41584846, 2025). "Treatment with MSI2 inhibitor FK228 could overcome LNC942‐induced cisplatin resistance in gastric cancer." (PMID 35073459, 2022). "In gastric cancer, LINC00942 binds with MSI2 and prevents its ubiquitination, whereas the overexpression of MSI2 can lead to the stabilization of MYC mRNA, which in turn promotes chemoresistance." (PMID 39075086, 2024). "Four genes, RBM15, FTO, MSI2 and ZC3H7B were identified as influencing the prognosis of gastric cancer patients in univariate analysis of 24 regulators." (PMID 36003776, 2022).
hepatocellular carcinoma (11 papers, 2014 to 2025). A malignant tumor that arises from hepatocytes. "For instance, the oncogenic RBP Musashi 2 (MSI2) was shown to be highly expressed in hepatocellular carcinoma, and was associated with cancer stem cell stemness and chemoresistance through the activation of LIN28A, another RBP." (PMID 38903178, 2024). "In conclusion, our study revealed that both MSI1 and MSI2 are abnormally expressed in hepatocellular carcinoma, but only the abnormal expression of MSI2 was associated with poor prognosis in a large series of hepatocellular carcinoma." (PMID 24305552, 2014). "This aligns with a previous report of lower LEF-1 (and TCF4) levels (protein and mRNA) upon MSI2 depletion in SMMC-7721 hepatocellular carcinoma cells." (PMID 40301545, 2025). "MSI2 is also related to Wnt signaling and may influence hepatocellular carcinoma outcomes through dysregulation of Wnt signaling." (PMID 31694854, 2020). "Moreover, MSI2 knockdown decreases the growth of glioblastoma and medulloblastoma cells and inhibits cell invasion in hepatocellular carcinoma." (PMID 27092875, 2017). "Besides, MSI2 might enhance invasion of hepatocellular carcinoma by inducing epithelial-mesenchymal transition." (PMID 39097735, 2024). "Importantly, the Msi2-reporter mouse we developed may be valuable not only for identifying LSCs but for a broader range of aggressive cancers with highly upregulated Msi2 expression, such as hepatocellular carcinoma, glioblastoma and breast cancer." (PMID 33243988, 2020).
non-small cell lung carcinoma (8 papers, 2020 to 2025). A group of at least three distinct histological types of lung cancer, including non-small cell squamous cell carcinoma, adenocarcinoma, and large cell carcinoma. "Furthermore, elevated MSI2 expression drives oncogenesis and facilitates distant dissemination across multiple malignancies, including leukemias, non-small cell lung cancer (NSCLC) and breast cancer." (PMID 41049614, 2025). "KLF4 also inhibits the tumor proliferation and metastasis of non-small cell lung cancer (NSCLC) through downregulating cyclin D1, upregulating p21, and inhibiting MSI2: an activator of the JAK/STAT3 signaling pathway that promotes metastasis." (PMID 37760529, 2023). "For example, in non-small cell lung cancer (NSCLC), elevated MSI2 expression was first detectable in early stage tumors, and continued to rise during tumor progression." (PMID 34237057, 2021). "MSI2 depletion significantly down-regulates EMT markers (TGF-β receptor 1, SMAD3, SNAI1 and SNAI2) to inhibit non-small cell lung cancer metastasis." (PMID 31952541, 2020).
bladder cancer (7 papers, 2017 to 2023). "Inspired by the correlation of DANCR and the miR-149/MSI2 axis in bladder cancer, they verified the combination of DANCR and miR-149 and the inverse correlation between MSI2 and miR-149." (PMID 37426488, 2023). "DANCR had been described to competitively bind miR-149 to positively regulate MSI2 expression and promote tumor malignant phenotypes in the pathogenesis of bladder cancer." (PMID 31827393, 2019). "The results indicated that DANCR promoted tumorigenicity of bladder cancer cells via up-regulating MSI2." (PMID 30419948, 2018). "The results indicated that DANCR promotes malignant phenotypes of bladder cancer cells via MSI2-dependent manner." (PMID 30419948, 2018). "Mechanistically, we found that DANCR expression was statistically positively correlated with MSI2 expression in bladder cancer and knockdown of DANCR decreased MSI2 expression in bladder cancer cells." (PMID 30419948, 2018). "Our study reveals that DANCR functions as a miRNA sponge to positively regulate MSI2 expression through sponging miR-149 and subsequently promotes the malignant phenotypes of bladder cancer cells, thus playing an oncogenic role in bladder cancer pathogenesis." (PMID 30419948, 2018). "Meanwhile, we found knockdown of DANCR inhibited MSI2 and ki67 expression of bladder cancer cells in vivo." (PMID 30419948, 2018). "Moreover, knockdown of miR-149 reversed MSI2 expression and MSI2 overexpression reversed the malignant phenotype inhibition of bladder cancer cells induced by silencing DANCR." (PMID 30419948, 2018). "Moreover, knockdown of miR-149 reversed the inhibition of MSI2 expression and MSI2 overexpression reversed the malignant phenotype inhibition of bladder cancer cells induced by silencing DANCR." (PMID 30419948, 2018). "Elevated MSI2 protein promoted transcription and translation of proteins operating in essential oncogenic signaling pathways, subsequently promoting malignant phenotypes of bladder cancer cells." (PMID 30419948, 2018). "Moreover, MSI2 overexpression significantly reversed cell migration and invasion inhibition of bladder cancer cells induced by silencing DANCR." (PMID 30419948, 2018). "We further determined whether DANCR regulated malignant phenotypes of bladder cancer cells via MSI2-dependent manner." (PMID 30419948, 2018). "Furthermore, MSI2 may act as a prognostic biomarker in patients with cervical cancer, bladder cancer and oesophageal squamous cell carcinoma." (PMID 32828126, 2020). "Moreover, we found that DANCR and MSI2 were co-localized in bladder cancer cells." (PMID 30419948, 2018). "We found knockdown of DANCR decreased MSI2 expression and inhibited EMT of bladder cancer cells in vivo." (PMID 30419948, 2018). "We found that DANCR was significantly up-regulated in bladder cancer cells and DANCR functioned as a miRNA sponge to positively regulate MSI2 expression through sponging miR-149." (PMID 30419948, 2018). "The results showed that DANCR expression levels were statistically positively correlated with MSI2 expression levels in bladder cancer and knockdown of DANCR decreased MSI2 expression in bladder cancer cells." (PMID 30419948, 2018). "And they found that DANCR was distributed mostly in the cytoplasm and functioned as a miRNA sponge to positively regulate the expression of musashi RNA binding protein 2 (MSI2) through sponging miR-149 and subsequently promoted malignant phenotypes of bladder cancer cells." (PMID 33123287, 2020).
glioblastoma (7 papers, 2013 to 2023). The most malignant astrocytic tumor (WHO grade IV). "We demonstrate that knockdown of MSI2 significantly reduces the growth of DAOY cells as well as U87 and U118 glioblastoma cells." (PMID 23667531, 2013).
myelodysplastic syndrome (6 papers, 2016 to 2023). A clonal hematopoietic disorder characterized by dysplasia and ineffective hematopoiesis in one or more of the hematopoietic cell lines. "High MSI2 expression has been associated with shorter survival in CML, myelodysplastic syndromes, CLL and AML." (PMID 36509891, 2023). "In this study, the authors show that MSI2 is required for maintaining myelodysplastic syndrome stem cells in mice and that MSI2 expression predicts poor prognosis in patients affected by this disease." (PMID 26898884, 2016). "MSI2 is also involved in myelodysplastic syndrome (MDS) progression, as conditional deletion of MSI2 in mouse models led to a reversal of MDS phenotypes, and its overexpression resulted in MDS progression." (PMID 36076951, 2022).
ovarian carcinoma (6 papers, 2017 to 2024). A malignant neoplasm originating from the surface ovarian epithelium. "In addition, microRNA-149 could suppress the malignant phenotypes of ovarian cancer via downregulation of MSI2 and inhibition of PI3K/AKT pathway." (PMID 39097735, 2024). "Then, ovarian cancer cells were subjected to siRNA-based dual knockdown of MSI-1 and MSI-2." (PMID 34768932, 2021). "While chemosensitization has been described for both MSI-1 knockdown and MSI-2 targeting independently in ovarian cancer cells, radiation effects have not previously been investigated." (PMID 34768932, 2021).
cervical cancer (5 papers, 2017 to 2023). A primary or metastatic malignant neoplasm involving the cervix. "MSI2 expression is upregulated in cervical cancer cells, and knockdown of MSI2 inhibits the proliferation of cervical cancer cells." (PMID 34047477, 2021). "Although previous studies have shown promise for targeting Musashi RNA-binding protein 2 (MSI-2) in diverse tumors, the role and mechanism of MSI-2 for cervical cancer (CC) progression and the regulation of MSI-2 expression remains unclear." (PMID 29073938, 2017). "Furthermore, it triggers the progression of ovarian and cervical cancers by sequestering miR-128-3p and promoting the expression of cyclin-dependent kinase 14 (CDK14) and RNA-binding protein Musashi-2 (MSI2)." (PMID 37998733, 2023).
chronic lymphocytic leukemia (5 papers, 2021 to 2025). "Currently, a small-molecule inhibitor of MSI2, Ro 08-2750, is undergoing a pre-clinical study and has shown high in vivo efficacy against chronic lymphocytic leukemia (CLL), with more similar drugs are being tested." (PMID 37941042, 2023). "In chronic lymphocytic leukemia (CLL), MSI2 is implicated in CLL cell growth and survival, and correlates with worse clinical outcome." (PMID 36076951, 2022).
liver cancer (5 papers, 2019 to 2025). An epithelial or non-epithelial malignant neoplasm that arises from the liver. "We also found that the loss of miR-3144-3p induces MSI2 overexpression and contributes to liver cancer." (PMID 36599932, 2023). "Both the canonical expression of miR-3144-3p and MSI2 knockdown were associated with G1/S phase arrest in the liver cancer cells, as determined via flow cytometry analyses of PI-stained liver cancer cells." (PMID 36599932, 2023). "Given that EMT is closely associated with stemness 32 and that MSI2 has been reported to facilitate the stemness of liver cancer stem cells 33, 34, we determined whether prolonged DEHP exposure also confers TNBC cell stem-like properties." (PMID 39990676, 2025). "The ectopic expression of a canonical miR-3144-3p mimic significantly repressed both the tumor growth and proliferation of liver cancer cells, and MSI2 knockdown exerted similar effects on the same cells." (PMID 36599932, 2023). "Ectopic expression of a miR-3144-3p mimic suppressed MSI2, whereas cotransfection of an antisense miR-3144-3p (AS-miR-3144-3p) mimic rescued this effect in liver cancer cells (upper)." (PMID 36599932, 2023). "In addition, the canonical expression of miR-3144-3p and MSI2 knockdown significantly suppressed not only wound-healing efficacy but also the migratory and invasive potential of the liver cancer cells." (PMID 36599932, 2023). "Additionally, Met expression was repressed in the livers of siMsi2-treated mice, showing a downstream effect of Msi2 on Met expression in liver cancer in vivo." (PMID 36599932, 2023). "First, the regulation of canonical miR-3144-3p on MSI2 in liver cancer was confirmed." (PMID 36599932, 2023). "Finally, MET abundance was found to be significantly increased as a result of knocking down overexpressed MSI2 in liver cancer cells." (PMID 36599932, 2023). "Among these candidates, only MSI2 expression was inhibited in both liver cancer cell lines." (PMID 36599932, 2023). "MSI2 promotes the stemness and chemoresistance in liver cancer stem cells via LIN28A activation." (PMID 31952541, 2020). "Additionally, even though MSI2 target genes, such as MYC, LIN28A, and MET, have been extensively studied, the upstream mechanism driving MSI2 overexpression in liver cancer development remains unclear." (PMID 36599932, 2023). "Treatments with mouse-specific ADAR1-, MSI2-siRNA-, or SLC38A4-expressing plasmids suppressed tumorigenesis and tumor growth in a mouse model of spontaneous liver cancer." (PMID 36599932, 2023). "In this study, we investigated the oncogenic function of ADAR1 by promoting miR-3144-3p editing to simultaneously induce Musashi RNA-binding protein 2 (MSI2) and suppress solute carrier family 38 member 4 (SLC38A4) in human liver cancer." (PMID 36599932, 2023). "We then used Western blot analyses to confirm that when MSI2 was selectively suppressed, MET was also suppressed, and conversely, when MSI2 was overexpressed, the expression of MET was also increased in liver cancer cells." (PMID 36599932, 2023). "We then demonstrated that Musashi RNA-binding protein 2 (MSI2) was a specific target of miR-3144-3p and that MSI2 overexpression was due to excessive ADAR1-dependent over-editing of canonical miR-3144-3p in liver cancer." (PMID 36599932, 2023). "Next, to demonstrate whether individual modulation of ADAR1, MSI2, and SLC38A4 affects liver tumorigenesis in vivo, we prepared H-ras-transgenic mice that spontaneously develop liver cancer beginning at ~14 weeks of age13." (PMID 36599932, 2023). "Therefore, we predicted that MSI2, a Musashi RNA-binding protein, as a target of canonical miR-3144-3p and SLC38A4 (solute carrier family 38 member 4) is a target for edited ED_miR-3144(3_A < G) and performed additional functional studies with these protein in liver cancer." (PMID 36599932, 2023).
liver cancer (continued). "Notably, we observed a significant positive correlation between MSI2 expression and ADAR1 expression but a negative correlation between SLC38A4 expression reported in publicly available (TCGA_LIHC, ICGC_LIRI, and GSE77314) and our multistage liver cancer (Catholic_mLIHC; GSE114564) datasets." (PMID 36599932, 2023).